PPT1 (palmitoyl-protein thioesterase 1)
Diseases named in the same sentence as PPT1 in open-access papers (continued):
Sharing a sentence is not in itself a finding about the gene and the disease.
melanoma (17 papers, 2019 to 2025). A malignant, usually aggressive tumor composed of atypical, neoplastic melanocytes. "Loss of Ppt1 in mice, as well as PPT1 in various human models (melanoma cells, patient-derived fibroblasts, patient brain tissues), elevates both p62-positive aggregates and Ub-positive proteins." (PMID 35252181, 2022). "Studies have found that the combined use of anti-PD-1 antibodies and PPT1 inhibitor HCQ or DQ661 can induce autophagy in vivo in melanoma." (PMID 40814339, 2025). "Research shows that chloroquine derivatives improve anti-PD-1 therapy in melanoma by targeting palmitoyl protein thioesterase 1 (PPT1)." (PMID 38654302, 2024). "For example, in melanoma, inhibiting PPT1 enhances the efficacy of anti-PD-1 antibodies, potentially boosting T-cell mediated tumor destruction and revolutionizing melanoma therapies." (PMID 38067206, 2023). "In melanoma treatment, PPT1 inhibition significantly enhances the efficacy of anti-PD-1 antibodies, marking a substantial advancement in therapeutic strategies." (PMID 38067206, 2023). "HCQ has been reported to potentiate the effects of anti-PD-1 against B16 melanoma cells in C57BL/6 mice via the inhibition of palmitoyl-protein thioesterase 1 (PPT1)." (PMID 34181666, 2021). "Exposure of antigen-primed T cells to macrophage-conditioned medium derived from macrophages treated with PPT1 inhibitors enhanced melanoma-specific killing." (PMID 32780726, 2020). "PPt1 inhibition–induced IFN-β release was critical for the augmentation of antigen-primed T cell killing of melanoma cells." (PMID 32780726, 2020). "They proposed that targeting palmitoyl-protein thioesterase 1 (PPT1) by hydroxychloroquine (HCQ) or genetic Ppt1 inhibition can enhance the anti-PD-1 Ab efficacy in melanoma, which may be mediated by lysosome dysfunction." (PMID 36230955, 2022). "Interestingly, PPT1 inhibition by HCQ or DC661 also led to an increased effect of anti-PD-1 therapy in melanoma in vitro and in a murine in vivo model, echoing findings recently made in pancreatic cancer." (PMID 34771737, 2021). "Therefore, we conducted preclinical studies with the clinically used PPT1 inhibitor HCQ in 2 immunocompetent mouse melanoma models and demonstrated an enhancement of tumor response when anti–PD-1 Ab was combined with HCQ." (PMID 32780726, 2020). "Targeting PPT1 blocks mTOR signaling, which reduces tumor growth of melanoma in mouse models." (PMID 31117943, 2019). "Their study employed DC661, a selective inhibitor of palmitoyl-protein thioesterase 1 (PPT1), which led to lysosomal membrane permeabilization (LMP) and subsequent release of DAMPs in melanoma and colon cancer models." (PMID 40656384, 2025). "PPT1 inhibitors can enhance STING levels, leading to IFN release and augmentation of T cell–mediated killing in melanoma models." (PMID 36795483, 2023). "Inhibiting palmitoyl-protein thioesterase 1 (PPT1), a target of CQ derivatives like hydroxychloroquine (HCQ), enhances the antitumor efficacy of anti-PD-1 Ab in murine melanoma models." (PMID 32780726, 2020). "Here, we report that inhibiting palmitoyl-protein thioesterase 1 (PPT1), a target of chloroquine derivatives like hydroxychloroquine (HCQ), enhances the antitumor efficacy of anti–PD-1 Ab in melanoma." (PMID 32780726, 2020). "Recent studies have shown that inhibiting PPT1, a target for chloroquine derivatives such as hydroxychloroquine (HCQ) or GNS561, significantly boosts the antitumor effects of anti-PD-1 antibodies in melanoma treatment." (PMID 40814339, 2025). "It was reported that inhibition of PPT1 with specific PPT1 inhibitors hydroxychloroquine (HCQ) or dimeric CQ DC661 induced interferon‐β secretion in macrophages and enhanced the antitumor efficacy of the anti‐PD‐1 antibody in melanoma." (PMID 36018061, 2023). "In our melanoma study we see clear augmentation of T cell priming with PPt1 inhibition but not with genetic inhibition of upstream autophagy genes." (PMID 32780726, 2020).
Batten disease (15 papers, 2012 to 2025). "Neuronal ceroid lipofuscinoses type I and type II (NCL1 and NCL2) also known as Batten disease are the commonly observed neurodegenerative lysosomal storage disorder caused by mutations in the PPT1 and TPP1 genes respectively." (PMID 30541466, 2018). "The intracranial injections of AAV encoding human PPT1 (hPPT1) increased enzyme activity and rescued phenotypic features of Batten disease in a mouse model of CLN1 disease (Ppt1−/−)." (PMID 34684815, 2021). "Commonly known as Batten disease, the different subtypes are each caused by a mutation in a distinct ceroid lipofuscinosis neuronal (CLN) gene (PPT1/CLN1, TPP1/CLN2, CLN3, DNAJC5/CLN4, CLN5, CLN6, MFSD8/CLN7, CLN8, CTSD/CLN10, PGRN/CLN11, ATP13A2/CLN12, CTSF/CLN13)." (PMID 35252181, 2022).
epilepsy (12 papers, 2017 to 2025). A brain disorder characterized by episodes of abnormally increased neuronal discharge resulting in transient episodes of sensory or motor neurological dysfunction, or psychic dysfunction. "Evaluating the epilepsy and CMAR panels revealed 5 P/LP variants in genes that generally associate with homozygous recessive inheritance (QARS, CLN8, PPT1, CSTB, and FKRP) in heterozygous decedents, indicating that these are likely incidental findings." (PMID 38229148, 2024). "For example, CTSD was a known gene for epilepsy, whose ranking order moved upward from 10,126th to 1766th, while PPT1 increased its ranking from 9067th to 1464th." (PMID 31427480, 2019). "Three patients (P10, P11, and P12) did not carry any variation in the exon or exon-intron boundaries of PPT1 gene but their common clinical presentations like epilepsy, cerebral atrophy, and cerebellar atrophy indicated NCL." (PMID 30541466, 2018).
neuronal ceroid lipofuscinosis 1 (11 papers, 2015 to 2026). A condition associated with mutation(s) in the PPT1 gene, encoding palmitoyl-protein thioesterase 1. "Autosomal recessive mutations in the gene PPT1, which encodes for palmitoyl protein thioesterase 1, cause neuronal ceroid lipofuscinosis-1 (CLN1), which is one of fourteen types." (PMID 37998376, 2023). "Finally, the hub, PPT1, whose mutation is responsible for the neurodegenerative and lethal condition, Neuronal Ceroid Lipofuscinosis 1, links the EPI/NLF and AUT/CFD/NLF modules." (PMID 30420816, 2018). "PPT1 enzyme deficiencies are known to cause neuronal ceroid lipofuscinosis-1 (MIM 265730)." (PMID 26275418, 2015). "Enzymatic activity determined on dried blood spots was the main method used to screen for TPP1 and palmitoyl protein thioesterase 1 (PPT1) for the differential diagnosis with neuronal ceroid lipofuscinosis type 1 (NCL1)." (PMID 35425725, 2022). "The PPT1 enzyme activity in the blood of the affected individual was strikingly decreased (5% of residual activity) confirming the clinical diagnosis of neuronal ceroid lipofuscinosis-1 (MIM 265730)." (PMID 26275418, 2015).
hepatocellular carcinoma (8 papers, 2022 to 2025). A malignant tumor that arises from hepatocytes. "Inhibition of PPT1 augments anti-PD-1 immunotherapy by elevating major histocompatibility complex (MHC)-I expression on hepatocellular carcinoma cell surfaces and influences immunity via the recolonization and activation of cytotoxic CD8+ lymphocytes." (PMID 40066091, 2025). "Inhibition of PPT1 by Ezurpimtrostat has been shown to decrease hepatic tumor burden in a murine model of hepatocellular carcinoma by promoting lymphocyte infiltration into tumors in conjunction with anti-programmed death-1 (PD-1) therapy." (PMID 40066091, 2025). "An analysis of hepatocellular carcinoma (HCC) using the TCGA dataset highlights the significance of lysosomal genes, with PPT1 positioned as a key player." (PMID 38067206, 2023). "We found that PPT1 and FTL were highly expressed in hepatocellular carcinoma cell lines, while DAB2 and SAT1 were highly expressed in human hepatocytes." (PMID 37693905, 2023). "As indicated by the results, in agreement with the results of the public database tissue, PPT1 and ADCK3 expression was upregulated in three hepatocellular carcinoma cell lines (Huh-1, HepG2, and SK-HeP-1) in comparison with normal hepatocytes LX-2." (PMID 37434985, 2023).
neuroblastoma (7 papers, 2015 to 2020). Neuroblastoma (NB) is the most common solid, extracranial childhood tumor. "For example, PPT1/CLN1 was shown to interact with CTSD/CLN10 in SH-SY5Y human neuroblastoma cells, possibly due to their common function as lysosomal enzymes." (PMID 32430003, 2020). "For example, proteomics-based analyses in SH-SY5Y human neuroblastoma cells revealed that PPT1/CLN1, CLN3, and CLN5 interact with 23, 58, and 31 proteins, respectively." (PMID 32430003, 2020). "The same research group analyzed the palmitoyl protein thioesterase 1 (PPT1 or CLN1 protein) interactome in SH-SY5Y human neuroblastoma cells." (PMID 29485613, 2018). "Overexpression of CLN1 protects LAN-5 neuroblastoma cells from ceramide-induced apoptosis, whereas antisense treatment (leading to a reduced expression of PPT1) increased the susceptibility to undergo cell death." (PMID 28878621, 2017). "Furthermore, a quantitative analysis of PPT1 interaction partners in human neuroblastoma cells identified seven mitochondrial proteins including components of the pyruvate dehydrogenase and ATP synthase complexes and voltage dependent anion channel protein 212,17,18." (PMID 32257390, 2020). "Finally DBH, SLC25A1, and SLC25A13 all interact with PPT1/CLN1, CLN3, and CLN5 in SH-SY5Y human neuroblastoma cells." (PMID 32430003, 2020).
breast carcinoma (6 papers, 2017 to 2025). "ZDHHC7 was elevated in kidney cancer cell lines in both datasets, and PPT1 was highly expressed in cell lines from breast cancer tumors." (PMID 36760531, 2023). "We also observed across studies highly elevated expression of ZDHHC7 in kidney cancer cell lines and PPT1 in breast cancer cell lines, opening potential avenues for research into the role of these enzymes in these cancers." (PMID 36760531, 2023). "Expression of TBC1D9 and CEACAM6 was higher in GATA3 mutant MCF-7 cells, GATA3 mutant CAMA1 cells, and primary GATA3 mutant breast cancer cells, whereas expression of PPT1, CYBRD1, HOXC13, and AFF3 was higher in GATA3 wild type cells." (PMID 29262572, 2017). "In turn, lysosomal protein PPT1 was upregulated in colon cancer after prolonged hypoxia, while ALDH6A was upregulated in, e.g., breast cancer under hypoxia." (PMID 34440794, 2021). "In agreement with the data generated with transfected-endothelial cells, siRNA-mediated knock-down of PPT1 and PPT2 in the breast cancer cell line MDA-MB-231, which constitutively expresses TF, also reduced fXa-generation." (PMID 34359738, 2021).
Blindness (5 papers, 2007 to 2025). Blindness is the condition of lacking visual perception defined as a profound reduction in visual perception. "Similarly, PPT1 genetic variants in dog are also associated with neurologic abnormalities and blindness." (PMID 30541930, 2019).
Brain atrophy (4 papers, 2009 to 2021). Partial or complete wasting (loss) of brain tissue that was once present. "Similarly, and irrespective of sex, we found a significant attenuation of brain atrophy as reflected by decreased reduction in total brain weights of Ppt1−/− mice treated with PLX3397." (PMID 33115477, 2020).
retinal degeneration (4 papers, 2019 to 2022). Degeneration of the retina. "However, detailed information about the progression of retinal degeneration, the molecular changes associated with the retinal pathology, and the impact of PPT1 deficiency on specific retinal neurons, such as rod and cone photoreceptor cells or specific retinal interneurons, is limited." (PMID 31578378, 2019). "The study also indicated that Ppt1 is essential for photoreceptor viability in Drosophila, and Ppt1 mutants show light- dependent retinal degeneration secondary to intracellular accumulation of rhodopsins from Ppt1 disruption." (PMID 30541930, 2019). "To analyze the progression and extent of retinal degeneration in Ppt1 ko mice, we first determined the thickness of the entire retina, the inner retina (i.e. from outer plexiform layer to vitreal retina margin) and the inner nuclear layer in 45-, 112- and 240-day-old mutant and wild-type retinas." (PMID 31578378, 2019).
developmental delay (3 papers, 2014 to 2021). "A heterozygous single exon deletion of similar size was detected in PPT1 together with a pathogenic nonsense variant p.(Arg151*) in a patient (ID 10) originally suspected to have Angelman syndrome who suffered from atonic seizures, motor disturbances and developmental delay." (PMID 34469436, 2021). "Human genetic studies indicated that copy number variants (duplications and deletions) including CLN3, and possibly another gene in the CISD2/PPT1/CLN3 network, are over-represented in individuals with developmental delay." (PMID 24705017, 2014).
frontotemporal dementia (3 papers, 2017 to 2024). Frontotemporal dementia (FTD) comprises a group of neurodegenerative disorders, characterized by progressive changes in behavior, executive dysfunction and language impairment, as a result of degeneration of the medial prefrontal and frontoinsular cortices. "Palmitoyl-protein thioesterase 1 (PPT1), a member of the depalmitoylation enzyme group, has been linked to dementia-related conditions, particularly neurodegenerative diseases affecting adults, including AD and frontotemporal dementia." (PMID 39807377, 2024).
gastric cancer (3 papers, 2020 to 2023). A primary or metastatic malignant neoplasm involving the stomach. "Palmitoyl-protein thioesterase 1 (PPT1) is known to be widely and significantly overexpressed in a variety of cancers, including breast, thyroid, and gastric cancers." (PMID 35277179, 2022). "13-AC exhibited a cytotoxic effect on bladder and stomach cancer cell lines by inducing apoptosis through the regulation of hnRNPs F/H and PPT1 as well as the activation p38/JNK pathway and the inhibition of PI3K/Akt growth pathways." (PMID 32718084, 2020). "In addition, PPT1 is known to be widely and notably overexpressed in a variety of cancers, including breast, thyroid, and gastric cancers." (PMID 37434985, 2023).
Intellectual disability (3 papers, 2014 to 2019). "We compared the frequencies of rare CNVs (deletions and duplications combined) encompassing CISD2, PPT1, CLN3 and their gene network partners in unaffected controls and in individuals with intellectual disability phenotypes." (PMID 24705017, 2014). "The phenotypic spectrum is highly variable in CLN1 (PPT1) and CLN6 diseases and application of targeted next generation sequencing panels for seizures, intellectual disability or retinopathy, or whole exome sequencing will likely identify more patients with nonclassical NCL phenotypes." (PMID 31741823, 2019).
liver cancer (3 papers, 2022 to 2023). An epithelial or non-epithelial malignant neoplasm that arises from the liver. "GNS561, a PPT1 inhibitor, is a promising autophagy modulator as it has started a phase 2 clinical trial in liver cancer indication, combined with atezolizumab and bevacizumab, an assessment without precedent in the field." (PMID 37443736, 2023). "And importantly, targeting PPT1 by HCQ to augment the palmitoylation level of AEG-1 successfully suppressed liver cancer cell growth." (PMID 36276642, 2022).
pancreatic cancer (3 papers, 2016 to 2023). "We observed that PPT1 was up-regulated by 2.07-fold in the pancreatic cancer secretome." (PMID 27869176, 2016). "Our results indicated that CTSD, DNAJB11, and PPT1 were not related with overall survival of pancreatic cancer (data not shown)." (PMID 27869176, 2016).
schizophrenia (3 papers, 2019 to 2025). A major psychotic disorder characterized by abnormalities in the perception or expression of reality. "PPT1, which plays a crucial role in neuronal morphology and function, has been linked to schizophrenia, with higher enzymatic activity correlating with disease severity." (PMID 41013196, 2025). "Higher enzymatic PPT1 in FEP schizophrenia patients is significantly associated with increased PANSS scaling values, indicating more serious rates of developing psychosis." (PMID 31270934, 2019). "The higher PPT1 enzymatic levels in FEP schizophrenia patients were positively associated with larger PANSS scaling scores (r = 0.32, P = 0.0079 for positive scaling; r = 0.41, P = 0.0006 for negative scaling; r = 0.45, P = 0.0001 for general scaling; and r = 0.34, P = 0.0048 for PNASS-S scaling)." (PMID 31270934, 2019). "This longitudinal study compared the PPT1 enzymatic activity in FEP schizophrenia patients and healthy volunteers, and the former exhibited a significant 1.5-fold increase in PPT1 enzymatic levels (1.79 mmol/L/h/mL, and 1.18 mmol/L/h/mL; P < 0.05; 95% CI, 2.3-2.9 and 1.4-1.8)." (PMID 31270934, 2019). "After adjusting for sex, age, body mass index (BMI) and total serum protein, our data demonstrated that PPT1 enzymatic activity is significantly associated with schizophrenia and its Positive and Negative Syndrome Scale (PANSS) scores." (PMID 31270934, 2019). "Enzymatic activity of PPT1 may provide an important new view for schizophrenia disorders." (PMID 31270934, 2019).
Angelman syndrome (2 papers, 2021 to 2024). A neurogenetic disorder characterized by severe intellectual deficit and distinct facial dysmorphic features. "One motivation for employing the DR paradigm in Ppt1−/− mice was brought on by previous work, which demonstrated that dark-rearing mouse models of other developmental disorders, like Rett and Angelman syndromes, mitigated disease symptoms." (PMID 38798824, 2024).
Autoimmunity (2 papers, 2024 to 2025). The occurrence of an immune reaction against the organism's own cells or tissues. "Our results demonstrated that the PPT1 inhibitor HDSF was effective in controlling autoimmunity in B6.Sle1yaa mice." (PMID 38169466, 2024). "PPT1 inhibitors such as HDSF may be the first drug in its class to suppress autoimmunity while enhancing immunity against tumorigenesis and infection." (PMID 38169466, 2024). "PPT1 may be a great drug target to treat IFN-I-mediated autoimmunity, because its inhibition may simultaneously enhance cDC1-dependent cross-priming and suppress pDC-dependent IFN-I production." (PMID 38169466, 2024).
dementia (2 papers, 2021 to 2024). Loss of intellectual abilities interfering with an individual's social and occupational functions. "The PASS server's designation of PPT1 as a dementia treatment is likely to be based on the understanding of the role of PPT1 in neuronal health and its association with neurodegenerative disorders." (PMID 39807377, 2024). "This study investigated Juniperus phoenicea L., a plant used in traditional Chinese medicine, as a potential inhibitor of palmitoyl-protein thioesterase 1 (PPT1), an enzyme associated with dementia." (PMID 39807377, 2024). "This in silico approach targeted dementia treatment according to the established role of PPT1 in neuronal health and its links with neurodegenerative diseases." (PMID 39807377, 2024). "This in silico study was aimed at identifying potential inhibitors of PPT1 from J. phoenicea phytochemicals, given that PPT1 is a target for developing new dementia medications." (PMID 39807377, 2024). "This study used in silico methods to comprehensively evaluate the potential of J. phoenicea phytochemicals as novel PPT1 inhibitors for dementia treatment." (PMID 39807377, 2024). "Our findings demonstrated the potential of amentoflavone as a novel PPT1 inhibitor for dementia treatment." (PMID 39807377, 2024). "PPT1 is an excellent target for anti-dementia therapy, because of its critical role in maintaining protein homeostasis and its association with neurodegenerative diseases." (PMID 39807377, 2024). "Hence, further investigation of the role of J. phoenicea as an inhibitor of the PPT1 enzyme is necessary to advance dementia drug development." (PMID 39807377, 2024).